CAT (catalase)
Diseases named in the same sentence as CAT in open-access papers (continued):
Sharing a sentence is not in itself a finding about the gene and the disease.
cerebral palsy (2 papers, 2019). A group of disorders affecting the development of movement and posture, often accompanied by disturbances of sensation, perception, cognition, and behavior. "In term newborns, catalase gene and interleukin-6 gene polymorphisms are associated with higher susceptibility to cerebral palsy after hypoxia-ischemia." (PMID 31275228, 2019). "Catalase gene and interleukin-6 gene polymorphisms are associated with higher susceptibility to cerebral palsy after neonatal hypoxia-ischemia." (PMID 31275228, 2019). "The GPx1 P198L, but not CAT C-262T, genetic polymorphism was associated with non-Hodgkin's lymphoma, while the CAT C-262T, but not GPx1 P198L, genetic polymorphism was associated with cerebral palsy after perinatal hypoxic-ischaemic encephalopathy." (PMID 31781040, 2019).
childhood asthma (2 papers, 2025). "Gene polymorphisms in glutathione s-transferase Pi-1 (GSTP1) and catalase (CAT) can modulate the risk of childhood asthma, with certain variants linked to higher risk and others to a protective effect." (PMID 41006975, 2025). "The combination of GSTP1 gene rs1695 and CAT gene rs7943316 formed the best predictive model for assessing the risk of childhood asthma in the Fuzhou region." (PMID 40433469, 2025). "Association analysis results showed that SNPs at GSTP1 gene rs1695, rs4891, HMOX1 gene rs17878790, CAT gene rs7943316, and rs769217 loci are associated with the risk of childhood asthma in Fuzhou region." (PMID 40433469, 2025). "GSTP1 gene SNPs rs1695 A>G, rs4891 T>C, CAT gene SNP rs7943316 A>T are potential risk factors for childhood asthma in the Fuzhou region." (PMID 40433469, 2025). "Discuss the correlation between single nucleotide polymorphisms (SNPs) of the Glutathione s-transferase Pi-1 (GSTP1), Catalase (CAT), Heme oxygenase-1 (HMOX1), and Homo sapiens epoxide hydrolase 1 (EPHX1) genes and the risk of childhood asthma in Fuzhou." (PMID 40433469, 2025). "The genotype ATT, composed of CAT gene rs7943316, rs1049982, and rs769217, may represent a protective genotype for childhood asthma." (PMID 40433469, 2025). "The ATT haplotype composed of CAT gene rs7943316, rs1049982, and rs769217 may be protective against childhood asthma [P = 0.006, OR = 0.45 (0.25–0.79)]." (PMID 40433469, 2025). "To date, there is no research on the association between GSTP1, CAT, HMOX1, EPHX1 gene SNPs and the risk of childhood asthma in the Fuzhou region." (PMID 40433469, 2025).
chronic gastritis (2 papers, 2009 to 2022). Inflammation of the stomach that is chronic in nature. "It was found that the median values of superoxide dismutase, catalase increased in patients with chronic gastritis compared with the control group." (PMID 36009600, 2022). "In patients with CAG and CALG, there was an increase in superoxide dismutase, catalase, glutathione-S-transferase and glutathione peroxidase in plasma compared with the control group and patients with chronic gastritis." (PMID 36009600, 2022).
colon adenocarcinoma (2 papers, 2021 to 2022). "In line with our results, decreased CAT levels have previously been reported in serum and tumor tissue in colon adenocarcinomas and other cancers." (PMID 36232966, 2022). "Only, in patients with colon adenocarcinoma, CAT expression is significantly lower than in normal tissue, although this does not seem to affect survival." (PMID 33540681, 2021).
colon adenoma (2 papers, 2017 to 2022). An adenoma that arises from the colon. "Previous studies also demonstrated that butyrate as a key fermentation product of dietary fiber or FS obtained from other dietary fiber rich sources induces CAT expression in colon adenoma or cancer cells." (PMID 29258268, 2017).
contact dermatitis (2 papers, 2021 to 2024). An inflammatory skin condition caused by direct contact between the skin and either an irritating substance or an allergen. "Contact dermatitis was found to be accompanied with a significant reduction in SOD (p < 0.001), GPX (p < 0.001), and CAT (p < 0.001, p = 0.002) in the skin and serum, respectively, compared to the control." (PMID 34040528, 2021).
corneal ulcer (2 papers, 2012 to 2021). Area of epithelial tissue loss from corneal surface; associated with inflammatory cells in the cornea and anterior chamber. "In the present study, corneal ulcers in both dogs and cats showed oxidative stress in the form of elevated MDA and reduction in TAC and CAT in tear samples, which normalized to normal levels after therapy." (PMID 33816586, 2021). "A corneal ulcer is associated with local oxidative stress manifested by elevation in MDA and reduction in TAC and CAT; this oxidative process is present independent of the morphological type." (PMID 33816586, 2021).
cutaneous leishmaniasis (2 papers, 2017). Leishmaniasis affecting the skin. "A significant decrease in CAT and SOD activities in cutaneous leishmaniasis has been reported." (PMID 29258248, 2017).
cyst (2 papers, 2015 to 2021). A sac-like closed membranous structure that may be empty or contain fluid or amorphous material. "We demonstrate that mitochondrial-targeted catalase suppresses cyst progression and kidney pathology that is at least partly driven by mitochondrial ROS in these two mouse models of PKD." (PMID 34671066, 2021). "Finally, there are also genes involved in defense against oxidative damage such as catalase (kat), dps and ohr that ramp up expression 3- to 8-fold late (96 hours) in cyst development." (PMID 25758168, 2015).
disc degeneration (2 papers, 2024 to 2025). "Our investigations found that the expression levels of SOD2 and CAT were significantly reduced in disc degeneration, which may contribute to NPC dysfunction and disc degeneration." (PMID 41614764, 2025).
disseminated candidiasis (2 papers, 2017 to 2022). Systemic candidiasis occurs when Candida yeast enters the bloodstream and may spread (becoming disseminated candidiasis) to other organs, including the central nervous system, kidneys, liver, bones, muscles, joints, spleen, or eyes. "Taken together, photoinactivation of catalase presumably enhances immune cells to phagocytose fungal cells, thus preventing the potential disseminated candidiasis." (PMID 35119220, 2022). "However, our most surprising finding was that, in contrast to the generally held view, catalase is not essential for the virulence of C. albicans, at least in models of disseminated candidiasis." (PMID 28542620, 2017).
Dyskinesia (2 papers, 2019 to 2021). A movement disorder which consists of effects including diminished voluntary movements and the presence of involuntary movements. "We report the associations of DRD2 rs1799732, NRG1 rs3735781, CAT rs1001179, SOD2 rs4880, and SLC22A1 rs628031 with time to occurrence of dyskinesia under the univariate analysis." (PMID 31156712, 2019). "CAT rs1001179 and SOD2 rs4880 were previously associated with non-motor adverse effects of dopaminergic treatment as well as with the time to occurrence of dyskinesia." (PMID 33478114, 2021). "Associations of CAT rs1001179 and SOD2 rs4880 with certain non-motor AEs of dopaminergic treatment were already detected in our previous study in the same cohort of patients, but their association with dyskinesia has never been reported before." (PMID 31156712, 2019).
endocarditis (2 papers, 2012 to 2025). Inflammation of the endocardium. "Helcococcus ovis is a gram-positive, catalase-negative coccus that is associated with endocarditis in bovines." (PMID 23082192, 2012).
eosinophilia (2 papers, 2017 to 2023). "Hemoglobin, Catalase and HBMD levels did not change in Control, whereas in Main group hemoglobin levels increased by +9.5% and erythrocyte sedimentation rate and eosinophilia decreased from baseline by 67.5 and 66.0%, respectively." (PMID 28163748, 2017).
esophagitis (2 papers, 2019 to 2022). An acute or chronic inflammatory disease affecting the esophageal wall. "Additionally, lycopene can give protection against experimental esophagitis via increasing GSH levels and SOD and CAT enzyme activities, and decreasing MDA levels in the lycopene-treated group when compared with controls." (PMID 35878352, 2022).
Fever (2 papers, 2025 to 2026). Body temperature elevated above the normal range. "Analyzing catalase activity in different experimental groups, the 12-day-old rat in part A exhibited notable decreases in groups with fever (P < 0.01), fever with DMI, and DMI alone (P < 0.05) compared to the control." (PMID 40131987, 2025).
folate deficiency (2 papers, 2013 to 2023). A nutritional condition produced by a deficiency of FOLIC ACID in the diet. "The induction of oxidative stress in response to folate deficiency has also been previously reported through increases in ROS levels, as well as reduced expression and activity of antioxidant enzymes (i.e., catalase, sodium dismutase)." (PMID 37981683, 2023).
Giardia infection (2 papers, 2023 to 2024). "In serum, these proteins included intelectin-1b (Q80ZA0), catalase (P24270), and β-2-microglobulin (P01887), which showed greater expression during giardiasis with respect to other infections." (PMID 36675151, 2023). "SB also increased the activity of superoxide dismutase without significantly affecting the activity of catalase in the liver in experimental Giardia infection and healthy gerbils." (PMID 39203520, 2024).
head and neck cancer (2 papers, 2014 to 2023). A primary or metastatic malignant neoplasm affecting the head and neck. "Multivariate analysis for CAT and NBN polymorphisms with radiation-induced oral mucositis in presence of alcohol among head and neck cancer patients." (PMID 24594932, 2014). "In 2017, it was reported that the LD50 of β-lapachone did not correlate with NQO1:CAT in head and neck cancer." (PMID 36978989, 2023).
hepatitis C (2 papers, 2019 to 2024). "HD patients with hepatitis C (V) were initially characterized by lower CAT activity; however, after one year of treatment, an increase in its activity was observed." (PMID 39456817, 2024). "Moreover, on Hepatitis C virus infection, have been reported the antioxidant defence mechanisms modified by the virus, for example, changes on gene expression of SOD and CAT, yielding a cellular oxidative imbalance." (PMID 31653913, 2019).
hepatotoxicity (2 papers, 2022 to 2023). Toxicity that causes injury to the liver or impairs the liver function. "When SOD and catalase levels of the prophylactic group (group 3) were compared with those of the hepatotoxicity group (group 2), they were significantly higher (P < .001)." (PMID 36635913, 2023).
Hyperbilirubinemia (2 papers, 2014 to 2023). An increased amount of bilirubin in the blood. "The results of this study showed that the activity of SOD, the level of GSH and CAT of mice in the Bil group, which decreased significantly, while the level of MDA increased, suggesting that the liver suffered more serious oxidative stress after hyperbilirubinemia." (PMID 36985691, 2023).
Hyperoxaluria (2 papers, 2012 to 2015). Increased excretion of oxalates in the urine. "Oxidants in hyperoxaluria appear to be mainly mitochondria-derived and therefore impair the intracellular antioxidant defense systems including the activity of enzymes like superoxide dismutase (SOD) and catalase (CAT)." (PMID 25928142, 2015). "This is in line with previous studies, which demonstrated a transient increase of CAT activity as an adaptive response in the early stages of hyperoxaluria but not after 42 days of chronic EG exposure." (PMID 25928142, 2015).
hypertensive renal disease (2 papers, 2021 to 2022). "Catalase has been described as a critical player in SIRT3-Foxo3a-mediated EndMT in hypertensive renal disease." (PMID 34458332, 2021). "In addition, the aortic rings from normotensive rats incubated with superoxide scavenger (Tiron) or aortic rings from renal hypertensive rats incubated with peg-catalase, which degrades hydrogen peroxide (H2O2), showed reduced contractile effect stimulated by phenylephrine." (PMID 36457305, 2022).
hypovitaminosis D (2 papers, 2025). "The analysis of the vitamin D status related to the age of the patients noted a slightly higher average value of the age of patients with hypovitaminosis D compared to the average value of the age corresponding to an optimal level both in patients with CAT and in those with GD." (PMID 40364199, 2025).
immunodeficiency (2 papers, 2014 to 2024). Failure of the immune system to protect the body adequately from infection, due to the absence or insufficiency of some component process or substance. "In superoxide dismutase (SOD)- and catalase (CAT)-deficient D. melanogaster, the immunodeficiency disorders were partially attributed to a defect in H2O2 metabolism." (PMID 24662974, 2014).
iron-overload (2 papers, 2016 to 2022). "In the iron-overload group, SOD, GSH-Px, Catalase and GSH values were lower than in the control group." (PMID 27649133, 2016).
laryngeal carcinoma (2 papers, 2014 to 2021). Carcinoma that arises from the laryngeal epithelium. "The influence of serum zinc levels on survival in laryngeal cancer patients can be multiplied if correlated with adequate antioxidant enzymes polymorphisms: SOD2 TC/TT and CAT CC." (PMID 34200699, 2021). "The goal of the current study was to evaluate whether circulating zinc levels, at the time of diagnosis, and polymorphisms in SOD2, CAT and GPX1 are associated with survival among laryngeal cancer patients." (PMID 34200699, 2021).
leishmaniasis (2 papers, 2017 to 2025). Infectious disease that is transmitted through the bite of hematophagous female phlebotomine sand flies. "Further, to prove the effect of leishmaniasis on the oxidant/antioxidant imbalance in the dermal tissue, the alteration of antioxidant enzymes was studied, including the activity of SOD and CAT enzymes." (PMID 29258248, 2017).
leukopenia (2 papers, 2022 to 2024). "Due to the immune system strengthening and anti-toxic properties of camel milk, in mice with leukopenia caused by CYP, hepatic SOD and CAT were increased compared to the untreated group." (PMID 39735585, 2024). "In addition, in mice with cyclophosphamide (CYP)-induced leukopenia, CM (1 ml, twice daily for 10 days) increased the levels of superoxide dismutase (SOD) and catalase (CAT) in liver homogenates, acting as an immune system booster." (PMID 35493477, 2022).
Lipedema (2 papers, 2022 to 2025). Disorder of adipose tissue characterized by symmetric and bilateral enlargement of the lower extremities due to abnormal deposition of subcutaneous fat often in obese women. "The same study also found higher concentrations of other oxidative stress markers in patients with lipedema, such as superoxide dismutase activity, catalase activity, and malondialdehyde concentrations, compared with a control group without lipedema." (PMID 40125475, 2025). "We found significantly higher MDA concentration and catalase and SOD activities in lipedema compared to the control group (p<0.01)." (PMID 36387874, 2022).
lysosomal storage disease (2 papers, 2015 to 2022). A metabolic disorder caused by mutations in proteins critical for lysosomal function, including lysosomal enzymes, lysosomal integral membrane proteins, and proteins involved in the post-translational modification and trafficking of lysosomal proteins. "Firstly, our results corroborate other studies that have shown an increase in the amount of activity in the CAT antioxidant enzyme in patients when compared to healthy controls, not only in GD, as well as in other lysosomal storage diseases (DLDs): Mucopolysaccharidosis type I and Fabry's disease." (PMID 26937402, 2015).
malignant glioma (2 papers, 2013 to 2021). A grade III or grade IV glioma arising from the central nervous system. "As a crucial factor in the acquisition of TMZ and radiation resistance, pharmacological inhibition of CAT activity is a promising strategy for the treatment of malignant gliomas, including highly aggressive GBM tumors." (PMID 34943091, 2021).
malignant mesothelioma (2 papers, 2014 to 2024). A malignant neoplasm of the pleura or peritoneum, arising from mesothelial cells. "Asbestos is also responsible for inducing an increase in the expression of antioxidant enzymes, including manganese-containing superoxide dismutase (MnSOD, SOD2), catalase, and heme oxygenase, in both malignant mesothelioma cells and the lungs of rodents." (PMID 38390570, 2024). "We show here that knockdown of PRX3 using targeted shRNAs in malignant mesothelioma cells (HMshPRX3) led to an increased mitochondrial oxidation state that was reversible through the over-expression of catalase or mito-catalase." (PMID 25462069, 2014).
melasma (2 papers, 2021 to 2023). "Remarkably, no reports were found on (pseudo)catalase or superoxide dismutase in melasma despite a submitted study in clinicaltrials.gov with oral-gliadin-protected SOD, last updated in September 2021." (PMID 38136202, 2023). "Therefore, it is difficult to state whether the lack of published studies about (pseudo)catalase/SOD in melasma also represents a lack of clinical efficacy." (PMID 38136202, 2023).
meningitis (2 papers, 2020 to 2026). A disorder characterized by acute inflammation of the meninges of the brain and/or spinal cord. "As expected, the experimental meningitis group showed decreased CAT levels in the PFC in both the 24-h (P < 0.01) and 10-day (P < 0.05) groups." (PMID 31901235, 2020). "A decrease in enzymatic defense, such as SOD and CAT levels, was observed in both the PFC and hippocampus of the meningitis rats." (PMID 31901235, 2020).
mental disorder (2 papers, 2019 to 2026). A disease that has its basis in the disruption of mental process. "Oxidative stress is intrinsically linked to mental disorders, involving an imbalance between reactive species and antioxidant defenses, where catalase is an essential, ubiquitous antioxidant enzyme." (PMID 42075972, 2026).
metastatic melanoma (2 papers, 2009 to 2022). A melanoma that has spread from its primary site to another anatomic site. "Compared to dysplastic nevus, our data shows that catalase expression decreased through the vertical growth phase and metastatic melanoma." (PMID 35326089, 2022).
Miscarriage (2 papers, 2023 to 2024). A pregnancy that ends at a stage in which the fetus is incapable of surviving on its own, defined as the spontaneous loss of a fetus before the 22th week of pregnancy. "The group of healthy pregnant women had higher average plasma copper concentrations and antioxidant enzyme activities (glutathione peroxidase and catalase) than the groups of spontaneous abortions and miscarriages." (PMID 39683462, 2024). "Previous studies have also demonstrated decreased selenium levels, catalase and glutathione peroxidase activities, and increased MDA and lipid peroxides in serum and/or placental tissues of recurrent miscarriage patients." (PMID 37398572, 2023).
muscle atrophy (2 papers, 2020 to 2022). The loss of muscle tissue due to inactivity or disease. "Our results showed that anti‐oxidative enzyme (SOD, CAT and GSH‐Px) activity was decreased, and ROS and MDA productions were increased in CKD‐induced muscle atrophy, and in TNF‐α‐induced C2C12 cells." (PMID 32910538, 2020).
myoma (2 papers, 2009 to 2019). "In comparison with polyps and myoma, the protein level of CAT was decreased in subjects with hyperplasia simplex (p = 0.005, p = 0.045, respectively) and adenocarcinoma (p = 0.001, p = 0.002, respectively)." (PMID 30978928, 2019). "Activity of CAT was significantly decreased in adenocarcinoma patients when compared to women with polyps or myoma." (PMID 20030853, 2009). "Compared to polyps and myoma subjects, patients with simple and complex hyperplasia did not have significantly lower CAT activity (p > 0.05), while in adenocarcinoma patients the activity was lower by 43% (p < 0.05)." (PMID 20030853, 2009).